AMH (anti-Mullerian hormone)
Diseases named in the same sentence as AMH in open-access papers (continued):
Sharing a sentence is not in itself a finding about the gene and the disease.
Insulin resistance (continued). "This surgery results in reduced BMI and waist circumference, with improved insulin resistance and glucose tolerance, vitamin D, SHBG, FSH and total and free testosterone, inhibin B and AMH, and reduced estrogen and prolactin." (PMID 34829704, 2021). "Serum levels of AMH, adiponectin, gonadotropins, androgens, total antioxidant capacity (TAC), nitricoxide (NO) and insulin resistance (IR) were measured by standard methods." (PMID 32112632, 2020). "Additionally, future research should measure a comprehensive set of reproductive (such as AMH, LH, FSH, and testosterone) and metabolic markers (such as insulin resistance and lipid profiles) before and after IF intervention." (PMID 41149632, 2025). "The exact relationship between insulin resistance and Anti-Müllerian hormone (AMH) has not been fully elucidated." (PMID 33763302, 2021). "The increased AMH production in PCOS patients may be related to elevated LH, androgen levels, and insulin resistance." (PMID 33602276, 2021). "In conclusion, miR differed in the follicular fluid between PCOS and normal control women, correlating with age, FAI, inflammation and AMH in PCOS, and with fertilization rate, insulin resistance and FAI and inflammation in control women, in accord with the Ingenuity pathway assessment." (PMID 31705013, 2019). "MiRNAs differed in the follicular fluid between PCOS and normal control women, correlating with age, FAI, inflammation and AMH in PCOS, and with BMI, fertilization rate (3 miRNA), insulin resistance, FAI and inflammation in control women, according to Ingenuity Pathway Analysis." (PMID 31705013, 2019). "Thus, women with high free T have numerous characteristics of PCOS: ovarian aspects (an increase in AMH as well as ultrasound features), hormonal aspects (a higher LH/FSH ratio), and also metabolic aspects (BMI, insulin levels, and insulin resistance)." (PMID 30275830, 2018). "The correlation between the AMH and HOMA-IR values should be interpreted with caution, as AMH might be a predictor of insulin resistance." (PMID 29426356, 2018). "In both Met-anov and Met-ov groups, and without difference between them, serum androgens and AMH, and indices of insulin resistance were significantly (p < 0.05) improved after treatment." (PMID 20663178, 2010). "Furthermore, other factors such as androgen, anti-Mullerian hormone (AMH), leptin, and insulin resistance are hypothesized to have a positive impact on the LH:FSH ratio, while adiponectin will decrease the LH:FSH ratio." (PMID 38589425, 2024). "Plus the authors did not observe a correlation between AMH levels and insulin resistance index." (PMID 37381009, 2023). "However, there are no clear correlations between levels of AMH with the incidence of insulin resistance in PCOS patients." (PMID 29426356, 2018). "However, there are no clear correlation between levels of AMH with the incidence of insulin resistance in PCOS patients especially in Indonesia." (PMID 29426356, 2018).
ovarian dysfunction (59 papers, 2011 to 2026). The inability of the ovaries to function. "Further large studies are needed to find the possible associations between the early prenatal AMH increase, Müllerian duct abnormalities, and ovarian dysfunction later in life." (PMID 41515619, 2026). "The objective of this study was to elucidate the intricate association between serum levels of AMH and ovarian dysfunction in a more comprehensive manner." (PMID 39629049, 2024). "AMH (Anti-Müllerian Hormone) allowed detection of a preserved but severely diminished ovarian reserve with a POI (Premature Ovarian insufficiency) onset risk." (PMID 31938033, 2020). "Several longitudinal studies about ovary-sparing hysterectomy with ovarian reserve have shown that premenopausal hysterectomy can cause earlier ovarian failure and decrease AMH levels one year after the procedure." (PMID 33259542, 2020). "This study is first to evaluate TEAS as a potential therapy to attenuate irradiation-induced ovarian failure through inhibiting primordial follicles loss, increasing serum AMH secretion, inducing antioxidant, and anti-apoptotic systems." (PMID 31324205, 2019). "Ovarian dysfunction, a major cause of infertility, can manifest with anovulatory cycles, elevated follicle-stimulating hormone levels, and diminished ovarian reserve markers such as anti-Müllerian hormone (AMH) levels or the Antral Follicle Count (AFC)." (PMID 39274502, 2024). "The predictive value of the ovarian reserve and whether lower AMH in BRCAm carriers places breast cancer patients at a higher risk for chemotherapy-induced ovarian failure were recently investigated." (PMID 34627117, 2021). "As women with ovarian endometrioma and a very low serum AMH level are expected to be at high risk of impending ovarian failure after cystectomy, IVF treatment before cystectomy may offer better pregnancy outcome for them." (PMID 21651823, 2011). "To assess whether ovarian dysfunction was associated with increased ovarian AMH expression in our mouse model, we first identified the percentage of both pre-antral and antral follicles that precisely expressed AMH as observed in the ovarian 3D data set." (PMID 37898094, 2023). "While AMH provides significant predictive power, its limitations in accurately predicting permanent ovarian insufficiency highlights the need for further research to refine its clinical utility." (PMID 40848466, 2025). "For instance, AMH’s high loading on a hormonal factor aligns with its role as a marker of ovarian dysfunction in PCOS." (PMID 41220482, 2025). "A rat model of DOX-induced failure of ovaries was used in the experiment for this study: Serum levels of E2, FSH, LH, and AMH were measured in the current investigation to verify ovarian failure." (PMID 40954150, 2025). "Serum AMH is secreted by the granulosa cells of the early follicle and is considered an important marker of ovarian failure." (PMID 39576415, 2025). "The extent to which AMH can serve as the most valuable indicator of ovarian dysfunction remains to be substantiated through further investigation." (PMID 39629049, 2024). "In clinical and experimental research, AMH was also thought to be a sensitive biomarker of iatrogenic ovarian failure." (PMID 39858407, 2024). "The study’s strengths lie in its utilization of extensive datasets and thorough examination of the correlation between FSH and AMH, which substantiates the notion that AMH is a more sensitive indicator of ovarian dysfunction compared to FSH." (PMID 39629049, 2024). "In this context, the use of mesenchymal stem cells in the treatment of ovarian insufficiency resulting from chemotherapy in rats was able to increase estrogen (E2) and anti-Müllerian hormone (AMH) concentrations." (PMID 38737577, 2024). "Investigate the effect of liraglutide on markers of ovarian dysfunction: bleeding ratio, ovarian morphology, levels of AMH and androgens, in women with PCOS." (PMID 39262529, 2024).
ovarian dysfunction (continued). "The patient returned four years later presenting an ovarian insufficiency with 0.23 ng/mL AMH levels and 21 IU/l FSH after the cessation of her oncological treatment and disease-free diagnosis." (PMID 37374137, 2023). "Peripheral AMH concentrations are increasingly been used as biomarker of ovarian dysfunction in human reproduction and fertility." (PMID 33763463, 2021). "Specific suggestions included detailed information on “ovarian failure”, “AMH”, “age statistics” and “genetics”." (PMID 32695432, 2020). "The comprehensive analysis of serum E2, FSH, and AMH indicated that the rat models of CUMS exhibited signs of ovarian dysfunction." (PMID 32685448, 2020). "AMH was also considered as a sensitive indicator of the iatrogenic ovarian failure in human and experimental studies." (PMID 31324205, 2019). "AMH is considered to be the most sensitive marker for ovarian failure and represents the ovarian reserve more closely." (PMID 26465611, 2015). "Evidence of ovarian insufficiency includes elevated gonadotropins, low anti-mullerian hormone (AMH) levels, and reduced mean ovarian volume." (PMID 25295241, 2014). "Therefore, the observation of a significantly reduced serum concentration of AMH in pSS compared to control seems to be a feature of ovarian dysfunction in pSS patients during childbearing age as previously suggested by Karakus and colleagues." (PMID 39576415, 2025). "•Pretreatment AMH level poorly predicts permanent ovarian insufficiency." (PMID 40848466, 2025). "While AMH is often used to predict ovarian reserve, it has become apparent that higher AMH levels may reflect a larger quantity of follicles, which could be indicative of ovarian dysfunction in PCOS." (PMID 40150054, 2025). "However, the predictive value of pretreatment AMH for permanent ovarian insufficiency is too limited to determine the postmenopausal status sufficiently accurately to switch upfront to another endocrine treatment, the aromatase inhibitors." (PMID 40848466, 2025). "Another treatment performed with MSCs was able to increase the concentrations of estrogen (E2) and anti-Müllerian hormone (AMH) in rats affected by ovarian insufficiency, demonstrating both the hormonal and tissue applicability that cellular treatment can have in animal reproduction." (PMID 38737577, 2024). "AMH should be used to evaluate chemotherapy-associated ovarian dysfunction after treatments, but it is well known that AMH does not predict the probability to achieve pregnancy." (PMID 35626104, 2022). "However, in those patients with a transient ovarian dysfunction, a rapid increase in AMH levels was highlighted up to two years after treatment." (PMID 34944951, 2021). "At present, the key diagnostic indicators of ovarian insufficiency include age, follicle-stimulating hormone (FSH) levels, anti-Mullerian hormone (AMH) levels, inhibin B levels, antral follicle count (AFC), ovarian stromal blood flow, and baseline ovarian volume." (PMID 34094652, 2021). "In addition, the level of AMH is significantly related to age, reflect changes of ovarian function during chemotherapy and predict ovarian failure after chemotherapy." (PMID 31413747, 2019). "Assessment of ovarian reserve by serum AMH levels before cystectomy may help to prevent ovarian failure after cystectomy." (PMID 21651823, 2011). "By examining the serum sex hormone levels, we found that the levels of AMH and E2 were extremely low in the CY/BUS group, and the hormone levels were significantly greater after COS treatment, further confirming that COS reversed the pathological ovarian hypofunction caused by CY/BUS modeling." (PMID 33494759, 2021). "AMH is the preferred serological marker for ovarian reserve owing to the constancy of its levels throughout the menstrual cycle, absence of feedback regulations, greater sensitivity to pick up early ovarian dysfunction, and better correlation with primordial follicular pool." (PMID 32799907, 2020).
ovarian dysfunction (continued). "In addition, because AMH level is strongly correlated with the size of the follicle pool and because of the lack of cycle variations, plasma levels of AMH are a good candidate for assessment of other ovarian dysfunctions." (PMID 24959584, 2014). "Diminished ovarian reserve, indicated by high follicle stimulating hormone (FSH), low anti-mullerian hormone (AMH), low antral follicle count and poor response to fertility treatment, is on the spectrum of ovarian dysfunctions." (PMID 39257928, 2024). "Women with transfusion-dependent SCD have significantly lower levels of FSH, LH,estrogen, andAMH.Similarly, those undergoing HSCT had undetectable AMH and FSH levels correspondingto menopause, suggesting profound ovarian insufficiency." (PMID 39626006, 2024). "AMH provides a more stable and consistent measurement, while FSH helps confirm the diagnosis and assess the severity of ovarian insufficiency." (PMID 39629049, 2024). "For example, as expected, low AMH levels (0.17–1.92 ng/ml) and high FSH levels (4.55–12 IU/L) were observed for women with ovarian dysfunction." (PMID 36697494, 2023). "In the present study, extremely high FSH levels and low AMH levels were observed in the VCD group, indicating that VCD-treated mice exhibited a typical ovarian failure." (PMID 33888135, 2021). "Patients with POF have elevated levels of FSH and E2 (cycle day 3) and considerably lower levels of AMH, as well as low AFC levels which have been used as markers of ovarian failure." (PMID 31531182, 2019). "Five of them reported amenorrhea, three irregular menses and all presented AMH levels below the LoQ and/or FSH levels consistent with ovarian failure." (PMID 31672154, 2019). "Recently, the protective effects of drugs on chemotherapy-induced ovarian dysfunction are usually evaluated by the measurement of follicle-stimulating hormone (FSH), estradiol, inhibin B, and AMH in plasma samples." (PMID 24959584, 2014). "Objective parameters to define chemotherapy-induced ovarian failure are follicle-stimulating hormone (FSH) and serum estradiol serum; while anti-Mullerian hormone (AMH) and antral follicle count (AFC) at ultrasound imaging are used to define the ovarian reserve." (PMID 39199566, 2024). "PH offspring have abnormal estrous cycle, decreased serum anti-Mullerian hormone (AMH), and increased serum follicle-stimulating hormone (FSH), and follicular atresia, which are consistent with the clinical manifestations in patients with ovarian dysfunction." (PMID 35257353, 2022). "Ovarian insufficiency was detected in one 17-years old girl with normal secondary sexual characteristics for age, with secondary amenorrhea, high concentration of FSH and low levels of AMH." (PMID 30744584, 2019). "Therefore, although COVID-19 changes the microenvironment of follicles leading to ovarian dysfunction, it does not have meaningful changes in indicators of ovarian reserve function such as AMH." (PMID 39635583, 2024). "The support also favored the increase of the Anti-Mullerian Hormone (AMH) levels and the decrease of circulating FSH in ladies of advanced reproductive age, which seems to imply some oxidative mechanisms affecting the hypothalamus-pituitary axis in the onset of ovarian failure." (PMID 27423667, 2016). "However, administration of both CAR or thymol alone increased the AMH levels when compared to the control rats (data not shown), a result which sheds lights on the potential ovarian preservation effect of these phenolic compounds in other forms of ovarian insufficiency." (PMID 31531182, 2019).
Obesity (54 papers, 2017 to 2026). Accumulation of substantial excess body fat. "Yet, little is known about AMH levels among women from ethnic minority populations, especially its associations with age and obesity." (PMID 40108611, 2025). "Several risk factors identified in this study-including obesity, elevated androgen levels, high AMH levels, and diabetes-are also well-recognized contributors to PCOS38, which itself is considered a significant risk factor for CI." (PMID 41387944, 2025). "It is well-documented that PCOS presents with higher serum concentrations of AMH and an increased risk of obesity and other metabolic disorders." (PMID 38926704, 2024). "Among the individuals with obesity, AMH was found to be the most effective diagnostic parameter for PCOS (AUC = 0.879), with a sensitivity of 73.13%, specificity of 89.58%, and cut off value of 5.63." (PMID 38600539, 2024). "In this study, we were unable to observe a significant association between obesity and AMH concentration." (PMID 35835777, 2022). "There is, however, no previous study investigating the circulating AMH levels in women with severe obesity and how a structured diet-induced weight loss program affects circulating AMH levels in these women." (PMID 36309748, 2022). "AMH levels were inversely associated with age, hypertension, medication use for hyperlipidemia, obesity, and BMI." (PMID 35831405, 2022). "LH and FSH, testosterone, and AMH are associated with obesity, metabolic syndrome, and type 2 DM in both sexes." (PMID 36471299, 2022). "For example, AMH levels gradually decline with older age and are negatively affected by chemotherapy, history of ovarian surgery, use of oral contraceptive pills (OCPs), obesity, presence of BRCA mutation and possibly Vitamin D deficiency." (PMID 41196903, 2025). "This significant difference draws attention to the association between obesity and low AMH levels." (PMID 38883018, 2024). "Further, low AMH may lead to hormonal disorders and an increased rate of obesity, therefore increasing the risk of cardiovascular disease." (PMID 37061732, 2023). "Moreover, diet-induced weight loss in women with PCOS and overweight or obesity, reduce or normalize AMH-levels." (PMID 36309748, 2022). "In this group of women with severe obesity, a weight loss beyond 12% could be needed to detect improvements, both in androgen levels and in circulating AMH." (PMID 36309748, 2022). "Obesity and its associated metabolic endotoxaemia helps initiate a pro-inflammatory state characterised by raised serum IL-6 levels, which in turn is correlated with impairment of both Leydig (testosterone) and Sertoli cell function (AMH)." (PMID 28286655, 2017). "Obesity may be negatively associated with ovarian reserve decreasing circulating AMH." (PMID 38913250, 2025). "Likewise, the increased leptin production associated with obesity could directly suppress AMH production." (PMID 34300357, 2021). "Despite a high prevalence of obesity and overweight in Samoan women, serum AMH and its age related decline were similar to those reported in other populations." (PMID 40108611, 2025). "Patients with PCOS facing a metabolic component, including obesity, present with decreasing AMH levels." (PMID 40564059, 2025). "AMH is significantly lower in women with obesity than in women with normal weight and is inversely correlated with BMI, although not all the studies reported differences between women with normal weight or obesity." (PMID 38559698, 2024). "Various factors that influence the function of granulosa cells, such as obesity and metabolic factors, can affect AMH production." (PMID 38600539, 2024). "Meanwhile, consideration the close relationship between AMH and obesity related to the disorders of glucose and metabolism, close attention should be paid to the clinical intervention and treatment of PCOS." (PMID 38600539, 2024). "A meta-analysis reported that BMI is negatively correlated with AMH in patients with obesity who had or didn’t have PCOS." (PMID 39328462, 2024).